ADGRG6 (adhesion G protein-coupled receptor G6)
Diseases named in the same sentence as ADGRG6 in open-access papers (continued):
Sharing a sentence is not in itself a finding about the gene and the disease.
tumor (14 papers, 2019 to 2026). "Taken together, these findings suggest that increased ADGRG6 expression is closely associated with higher pathological grade and larger tumor burden, both key indicators of aggressive tumor behavior in PAAD." (PMID 41614755, 2025). "The primary endpoints of this study were (i) the association between ADGRG6 expression and patient prognosis and (ii) the functional and mechanistic evidence linking ADGRG6 to tumor progression and immune regulation in PAAD." (PMID 41614755, 2025). "Recent studies have implicated ADGRG6 in tumor progression and immune regulation, suggesting it as a promising candidate for cancer diagnostics and therapy." (PMID 41614755, 2025). "Furthermore, several reports have linked integrins to tumor metastasis and immune escape, and we identified a potential relationship between ADGRG6 and integrins." (PMID 40226617, 2025). "Furthermore, ADGRG6 expression was positively correlated with tumor mutational burden (TMB) and microsatellite instability (MSI) across PAAD." (PMID 40226617, 2025). "For detecting, ADGRG6 enhancer mutations were usually using Sanger sequencing or NGS, but these methods are time‐consuming or sensitivity‐limited, which may result in an underestimation of the prevalence of ADGRG6 enhancer mutations when tumor samples contain a low percentage of mutations." (PMID 37081791, 2023). "Bioinformatics analyses revealed substantial upregulation of ADGRG6 in human PC, correlating with poor survival rates and advanced tumor stages." (PMID 42091867, 2026). "Through integrative multi-omics and functional validation, we demonstrate that ADGRG6 promotes tumor proliferation, invasion, and migration, partly via activation of the NF-κB→STAT6→GATA3 axis." (PMID 41614755, 2025). "In summary, our findings establish ADGRG6 as a multifaceted oncogenic regulator in PAAD that promotes tumor progression through both cell-autonomous mechanisms and potential immune-associated pathways." (PMID 41614755, 2025). "First, through clinical validation in a TMA cohort, we confirmed that ADGRG6 protein overexpression correlates with multiple aggressive tumor features, reinforcing its translational potential as a prognostic biomarker." (PMID 41614755, 2025). "Future studies employing immunocompetent or humanized mouse models will be essential to delineate the precise mechanisms through which ADGRG6 influences tumor–immune crosstalk and to evaluate its therapeutic potential in immune-relevant contexts." (PMID 41614755, 2025). "Further exploration of the relationship between ADGRG6 expression and various stages of the tumor immune cycle revealed distinct immune activity levels between the two groups, particularly during the priming and activation stages." (PMID 40226617, 2025). "Second, we revealed a previously uncharacterized connection between ADGRG6 and tumor-immune microenvironmental modulation." (PMID 41614755, 2025). "A comparative analysis of normal and tumor tissues revealed significantly elevated ADGRG6 expression in the ductal cells of tumor samples compared to those in normal tissue." (PMID 40226617, 2025). "Our findings align with and extend prior evidence implicating ADGRG6 in tumor progression across multiple cancer types." (PMID 41614755, 2025). "While their work revealed a tumor cell-intrinsic oncogenic mechanism, the immunological functions of ADGRG6 and its broader impact on the TME remain poorly defined." (PMID 41614755, 2025). "The results showed that ADGRG6 was significantly upregulated in PAAD tissues (Tumor, T, n = 179) compared with the normal population (Normal, N, n = 171) (* p < 0.05)." (PMID 41614755, 2025). "Analysis of the GSE71729, GSE15471, GSE183795, GSE62452, and GSE28735 datasets revealed that ADGRG6 expression was significantly higher in tumor samples compared to normal pancreatic tissues." (PMID 40226617, 2025).
tumor (continued). "To assess the role of ADGRG6 in the tumor microenvironment of PAAD, we evaluated immune infiltration using CIBERSORT, ssGSEA, xCell and Tracking Tumor Immunophenotype (TIP), and utilized single-cell sequencing data to explore cell-cell interactions." (PMID 40226617, 2025). "Subcutaneous transplantation experiments in nude mice indicated that ADGRG6 knockdown substantially suppressed growth of xenografted tumor of PAAD cells." (PMID 40226617, 2025). "To investigate the expression and potential tumor-regulatory role of ADGRG6, we analyzed expression data from the TCGA Pan-Cancer cohort and the GTEx database." (PMID 40226617, 2025). "ADGRG6 also promoted tumour-stromal angiogenesis and hypoxia-induced retinal angiogenesis through the GATA2/STAT5/ VEGF/MAPKs signalling pathway." (PMID 34809653, 2021). "Consistent with the WGCNA results, in the GSE15471 dataset, the TSPOAP1 in the tumor group was significantly lower expressed, while the ADGRG6, GPR87, FAM111B and MMP28 were significantly higher expressed compared with the normal group." (PMID 34809653, 2021). "A NGS assay showed that the tumor had a novel ROS1-ADGRG6 rearrangement generated by the fusion of exons of 1–33 of ROS1 on chr6: q22.1 to exons of 2–26 of ADGRG6 on chr6: q24.2." (PMID 31382924, 2019). "Therefore, although these models confirm the tumor-suppressive effects of ADGRG6 silencing on tumor proliferation and invasion, they cannot fully capture the complexity of ADGRG6-mediated immune modulation." (PMID 41614755, 2025). "Given these associations with immune-related markers, we next explored whether ADGRG6 directly contributes to tumor progression and immune signaling." (PMID 41614755, 2025). "Although the underlying mechanism remains unclear, this phenomenon may involve altered cytokine production or host–tumor metabolic interactions, warranting further investigation into the systemic safety profile of targeting ADGRG6." (PMID 41614755, 2025). "Increased ADGRG6 expression also correlated with an increase in tumor angiogenesis, supporting previous evidence that ADGRG6 may have a role more generally in angiogenesis via the VEGF signaling pathway." (PMID 33735533, 2021). "Notably, we find recurrent ADGRG6 enhancer mutations and FRS2 duplications which are associated with higher protein expression in the tumor and poor prognosis." (PMID 30755618, 2019). "Collectively, these results demonstrate that ADGRG6 exerts potent oncogenic effects in PAAD by promoting cellular proliferation, migration, invasion, and tumor formation, thereby supporting its potential role as a therapeutic target." (PMID 41614755, 2025). "Although xenograft findings require validation in immunocompetent models, our results highlight ADGRG6 as a potential oncogenic driver and therapeutic target in PAAD, linking tumor-intrinsic growth mechanisms with immune modulation within the TME." (PMID 41614755, 2025). "Single-cell RNA-sequencing data from the TISCH database further showed that ADGRG6 is expressed not only in malignant epithelial cells but also in endothelial and dendritic cell compartments, suggesting that it may participate in tumor–stroma and tumor–immune crosstalk." (PMID 41614755, 2025). "To validate the clinical significance of ADGRG6 expression, we performed IHC staining on a PAAD TMA containing 71 tumor samples." (PMID 41614755, 2025). "We hypothesized that ADGRG6 is overexpressed in PAAD and predicts unfavorable clinical outcomes by promoting tumor cell proliferation and migration through NF-κB/STAT6-mediated signaling and modulation of the TME." (PMID 41614755, 2025). "In this study, we tested the hypothesis that ADGRG6 is overexpressed in PAAD and drives tumor progression through NF-κB/STAT6-mediated signaling and modulation of the TME." (PMID 41614755, 2025).
tumor (continued). "Patients with high ADGRG6 expression had a worse OS in multiple subgroups, including sex, cancer stages 1–2, T2–3 (tumor size >2 cm but ≤4 cm, >4 cm), N0 (no regional lymph node metastasis), and M0 (no distant metastasis)." (PMID 41614755, 2025). "Intriguingly, ADGRG6 expression was significantly higher in these malignant cells compared to non-malignant cells within tumor samples." (PMID 40226617, 2025). "Similarly, a comprehensive whole-genome, transcriptome and clinical dataset called the POG570 cohort, had revealed that alterations in EGFR, ADGRG6, and other genes were involved in tumour drug resistance and sensitivity, as well as recurrent noncoding events." (PMID 34809653, 2021). "To investigate the expression pattern of ADGRG6 in PAAD, we first examined its mRNA levels in tumor and normal pancreatic tissues using the GEPIA database, which integrates RNA-seq data from TCGA and GTEx." (PMID 41614755, 2025).
cancer (10 papers, 2019 to 2025). A tumor composed of atypical neoplastic, often pleomorphic cells that invade other tissues. "Lollipop charts illustrating ADGRG6 protein mutations in the TCGA pan-cancer cohort indicated that missense mutations were the predominant mutation type." (PMID 40226617, 2025). "The finding of recurrent ADGRG6 enhancer mutations also facilitated our knowledge of underlying molecular mechanisms of pathological angiogenesis in the highly vascularized cancers." (PMID 35440045, 2022). "ADGRG6 can also form carcinogenic fusion variants with ROS1 to promote the development of EGFR-tyrosine kinase inhibitor resistance in cancer patients with EGFR mutation." (PMID 34809653, 2021). "ADGRG6 variants and transcriptional changes have also been associated with various human cancers." (PMID 33735533, 2021). "Although there are challenges for targeting ADGRG6, small molecule modulators have potential for therapeutic use against many ADGRG6‐disease linked conditions, including cancers where ADGRG6 overexpression may contribute to the disease (see Section 3)." (PMID 33735533, 2021). "Utilizing data from the TCGA, GTEx, HPA, CPTAC, and CCLE databases, we discovered abnormal mRNA and protein expression of ADGRG6 in several cancers including PAAD." (PMID 40226617, 2025). "In this study, we examined the expression patterns, epigenetics, and prognostic value of ADGRG6 in The Cancer Genome Atlas (TCGA) pan-cancer cohort using multi-omics approaches." (PMID 40226617, 2025). "Cancer cells can exploit immune checkpoints to evade immune responses, and the ADGRG6-high group displayed increased levels of CD274/PDL1 and SIGLEC15 expression." (PMID 40226617, 2025). "In this report, we first summarized the expression pattern of ADGRG6 across pan-cancer." (PMID 40226617, 2025). "Conversely, knockdown of ADGRG6 results in low expression of HDAC2 and GLI2, and inhibits proliferation and arrests cell cycle in cancer cells." (PMID 34809653, 2021). "As regulatory targets of some ncRNAs, TSPOAP1, ADGRG6, MMP28 and other genes are particularly important in the initiation, progression of various cancers such as PC." (PMID 34809653, 2021). "ADGRG6 was consistently associated with poor prognosis in PAAD, rather than other cancers, across all four evaluation methods." (PMID 40226617, 2025).
peripheral neuropathies (2 papers, 2015 to 2020). "We designed a dimeric Fc-fusion protein comprising the myelinotrophic domain of PrP (FT2Fc), which activated Adgrg6 in vitro and exhibited favorable pharmacokinetic properties for in vivo treatment of peripheral neuropathies." (PMID 33180885, 2020). "Many approved drugs target G-protein coupled receptors, and therefore Adgrg6 may represent an attractive potential target to stimulate repair in peripheral neuropathies or after nerve damage." (PMID 33180885, 2020).
myopathy (1 paper, 2020). A disease of the muscle in which the muscle fibers do not function properly. "We wondered whether treatment with FT2Fc may have mimicked PrP overexpression and induced gene expression changes similar to those involved in the myopathy phenotype rather than acting as a ligand to Adgrg6." (PMID 33180885, 2020).
peripheral nerve diseases (1 paper, 2020). "We here exploited a natural Adgrg6 agonist, PrP, to design a molecule targeting Adgrg6 for the treatment of peripheral nerve disease." (PMID 33180885, 2020). "Although our treatment regimen was not successful, Adgrg6 should not be discarded as a possible therapeutic target for peripheral nerve diseases." (PMID 33180885, 2020).
ADGRG6 also shares sentences with these, for which no sentence is quoted: breast carcinoma (7 papers); neuromuscular disease (3); colorectal cancer (2); cystitis (2); glioblastoma (2); infection (2); kidney disease (2); pancreatic adenocarcinoma (2); acute kidney injury (1); breast adenocarcinoma (1); cardiac failure (1); cerebral small vessel disease (1); cervical squamous cell carcinoma (1); chronic kidney disease (1); chronic obstructive pulmonary disease (1); chronic pancreatitis (1); colorectal tumors (1); connective tissue disorder (1); diabetes (1); endocervical adenocarcinoma (1); endothelial dysfunction (1); esophageal cancer (1); focal segmental glomerulosclerosis (1); gastric cancer (1); glomerular disease (1); head and neck squamous cell carcinoma (1); Hypertension (1); hypertensive nephropathy (1); IgA nephropathy (1); Intrauterine growth restriction (1).
A further 29 diseases each share a sentence with ADGRG6 in 1 paper.